PGR (progesterone receptor)
Diseases named in the same sentence as PGR in open-access papers (continued):
Sharing a sentence is not in itself a finding about the gene and the disease.
breast cancer (continued). "Triple-negative breast cancer (TNBC) is a definition encompassing all breast cancers with no/low immunohistochemically detectable expression of estrogen receptor α and progesterone receptor, and a lack of genomic amplification of ERBB2/HER2." (PMID 34684657, 2021). "Others report elevated serum levels of IL-8 and IL-13 in patients with no CTCs and progesterone receptor-negative breast cancer when compared to patients with progesterone receptor-positive breast cancer." (PMID 33809315, 2021). "Triple-negative breast cancer (TNBC) is a subset of breast cancer that does not express the estrogen receptor (ER), progesterone receptor (PR), and human epidermal growth factor receptor-2 (HER2), and accounts for approximately 20% of breast cancers." (PMID 33809079, 2021). "Breast cancer expresses clinically heterogeneous characteristics that show differential expression for estrogen receptor (ER), human epidermal growth factor receptor 2 (HER2), and progesterone receptor (PR)." (PMID 33807834, 2021). "Or interestingly, one could use the mouse breast cancer cell line MMTV-PyMY (ER−, PgR− Her2+/−) as a "pioneer" instead of MDA-MB-231 cells to observe cell competition phenomena without considering protein–protein interactions." (PMID 33649456, 2021). "Triple negative breast cancer (TNBC) is a subtype of breast cancer, which is lack of estrogen receptor (ER), progesterone receptor (PR) or human epidermal growth factor receptor 2 (HER-2)." (PMID 34201121, 2021). "Triple-negative breast cancer (TNBC) is a type of breast cancer that does not express estrogen receptor (ER), progesterone receptor (PR), or human epidermal growth factor receptor 2 (HER2) genes." (PMID 34830990, 2021). "Triple-negative breast cancer (TNBC) accounts for approximately 15–20% of all breast cancers and characterized by the lack of expression of estrogen receptor (ER), progesterone receptor (PR), and human epidermal growth factor receptor 2 (HER2)." (PMID 34123797, 2021). "In a Europe-wide external quality assessment, we compared performance of an mRNA-based method [Xpert® Breast Cancer STRAT4 (CE-IVD)] for determining ESR1, PGR, ERBB2, and MKI67 expression against the gold standard [immunohistochemistry (IHC)/HER2 in situ hybridization (ISH)]." (PMID 34572945, 2021). "The choice of breast cancer cell line for this work (MCF-7) was established from invasive ductal carcinoma (IDC) of a Caucasian patient and the cells are known to be estrogen (ER) and progesterone receptor (PgR)-positive." (PMID 33466869, 2021). "TNBC, which is the most aggressive subtype of breast cancer without an expression of the progesterone receptor, estrogen receptor, and human epidermal growth factor receptor 2, accounts for 10–20% of all breast cancers." (PMID 34737698, 2021). "In a sub-analysis of Black and White women with estrogen and progesterone receptor negative breast cancer at the HFHS, there was also no overall survival disparity after adjustment for deprivation index (HR 1.26, 95% CI 0.84-1.87)." (PMID 34336677, 2021). "Triple‐negative breast cancer (TNBC), a subtype of breast cancer that is characterized by lack expression of oestrogen receptor (ER), progesterone receptor (PR) and human epidermal growth factor receptor 2 (HER2), accounting for about 15% of all breast cancers." (PMID 33949761, 2021). "Triple-negative breast cancer (TNBC) is a subtype of breast cancer, which is commonly defined as the absence of estrogen receptor (ER), progesterone receptor (PR), and human epidermal growth factor receptor 2 (HER2)." (PMID 34326697, 2021). "Triple-negative breast cancer (TNBC) encompasses an heterogenous subtype of breast cancer that is histologically defined by the lack of estrogen receptor (ER), progesterone receptor (PR) and HER-2/neu overexpression." (PMID 33599863, 2021).
breast cancer (continued). "Breast cancer is divided into three subgroups based on the presence or absence of estrogen receptor (ER), progesterone receptor (PR), or human epidermal growth factor receptor 2 (HER2) overexpression." (PMID 34439317, 2021). "Triple-negative breast cancer (TNBC) is a breast cancer subtype defined by its lack of an estrogen receptor (ER) and progesterone receptor (PR), and the absence of amplification of human epidermal growth factor receptors 2 (HER-2)." (PMID 33919109, 2021). "TNBC refers to breast cancer that does not express the estrogen receptor (ER), progesterone receptor (PR), and HER2/neu genes." (PMID 33921192, 2021). "Triple-negative/basal-like breast cancer is hormone-receptor negative (estrogen-receptor and progesterone-receptor negative) and HER2 negative." (PMID 34660251, 2021). "Triple-negative breast cancer (TNBC) is a heterogeneous type of breast cancer that is characterized by the absence of expression of estrogen receptor (ER), progesterone receptor (PR), and human epidermal growth factor receptor-2/neu (HER-2)." (PMID 34474671, 2021). "According to the expression levels of estrogen receptor [ER], progesterone receptor [PR], and human epidermal growth factor receptor 2 [HER2] protein, breast cancer can be divided into four subtypes: luminal -A, luminal-B, HER-2 positive, and triple negative breast cancer (TNBC)." (PMID 33747905, 2021). "Triple-negative breast cancers (TNBCs) account for ~15% of all instances of mammary tumors without expression of estrogen receptor (ER), progesterone receptor (PR) and human epidermal growth factor receptor 2 (HER2)." (PMID 34712723, 2021). "TNBC is a subtype of breast cancer histologically defined by the lack of estrogen receptor (ER), progesterone receptor (PR), and HER-2 overexpression." (PMID 34659224, 2021). "In addition to breast cancer, ESR1, ESR2, and PGR also mediate the progression of prostate cancer, colon cancer, ovarian cancer, and lung cancer." (PMID 34322374, 2021). "Triple-negative breast cancer (TNBC) is an aggressive breast cancer negative for progesterone receptor (PR), estrogen receptor (ER), and human epidermal growth factor receptor 2 (Her-2)." (PMID 34965257, 2021). "Triple-negative breast cancer (TNBC) is a specific subtype of breast cancer that does not express an estrogen receptor (ER), a progesterone receptor (PR), or human epidermal growth factor receptor 2 (HER-2)." (PMID 34830111, 2021). "Triple-negative breast cancer (TNBC) is one of the subtypes of breast cancer, which is named because of the negative expression of estrogen receptor (ER), progesterone receptor (PR), and human epidermal growth factor receptor 2 (HER2)." (PMID 34771505, 2021). "Targets with the highest numbers of interactions with Chrysanthemum phytochemicals (degree = 6) including PGR, HEM6 and EHMT1 might be major therapeutic targets for breast cancer." (PMID 34083561, 2021). "The breast cancer subtype was luminal A type and was positive for estrogen receptor and progesterone receptor, and negative for HER2/neu and Ki-67 marker index <10% on immunohistochemistry." (PMID 33832078, 2021). "Triple-negative breast cancer (TNBC) is a, breast cancer (BCa) subtype with no expression of estrogen receptor (ER), progesterone receptor (PR), and human epidermal growth factor receptor 2 (Her2) protein." (PMID 34219129, 2021). "In breast cancer, conventional markers including estrogen receptor alpha (ERα) and progesterone receptor (PR), are indicators for hormonal treatment, but do not act as prognostic markers." (PMID 33832499, 2021). "TNBC is an aggressive breast cancer subtype, characterized by the lack of expression of estrogen receptor (ER), progesterone receptor, and human epidermal growth factor receptor 2 (HER2)." (PMID 34404439, 2021).
breast cancer (continued). "Triple-negative breast cancer (TNBC) is a specific subtype of breast cancer, which lacks the expressions of estrogen receptor (ER), progesterone receptor (PR) as well as human epidermal growth factor receptor 2 (HER-2)." (PMID 34666596, 2021). "For circ_0001750, a higher expression was found in breast cancer tissues with a higher tumor grade, negative progesterone receptor (PR), or higher Ki-67 expression." (PMID 35211507, 2021). "TNBC is a subtype of breast cancer that accounts for ∼20% of all breast cancers and is characterized by lacking estrogen receptor, progesterone receptor, and HER2 expression." (PMID 34874454, 2021). "Triple negative breast cancer (TNBC), defined as breast cancer cells lacking expression of oestrogen receptor, progesterone receptor, and human epidermal growth factor receptor 2 (HER2), accounts for up to 20% of all breast cancer." (PMID 34677445, 2021). "Another study assessed serum microRNAs as a possible biomarker of brain metastasis (BM) in patients with breast cancer and discovered that serum miR-4480 and PgR negative are useful biomarkers for predicting BM in patients with breast cancer." (PMID 33925295, 2021). "Triple negative tumors represent 15% of breast cancer and are characterized by the lack of estrogen receptors, progesterone receptor, and HER2 amplification or overexpression." (PMID 34900718, 2021). "This study aimed at using ICC-RNAseq to investigate the molecular implications of progesterone receptor (PR) negative conversion in hormone receptor positive Luminal A breast cancer, the most frequent breast cancer subtype among women." (PMID 34745451, 2021). "In a study of women with estrogen and progesterone receptor negative breast cancer at the HFHS, Black compared to White women were ten times more likely to reside in an area with the highest level of deprivation (45.9% vs 4.4%, respectively p< 0.001)." (PMID 34336677, 2021). "Magnetic resonance imaging revealed a well enhanced focal solid tumor in the right parietal lobe (5.0 × 4.2 cm in size), Immunohistochemical staining revealed cerebral metastases of breast cancer with HER2 subtype conversion (estrogen receptor +++, progesterone receptor +++, HER2 −)." (PMID 33725931, 2021). "Triple-negative breast cancer (TNBC), characterized by the absence of estrogen receptor, progesterone receptor, or human epidermal growth factor receptor-2, affects nearly 15% of women with breast cancer." (PMID 34458041, 2021). "TNBC shows the worst prognosis compared to other breast cancer types, because of the lack of three therapy-relevant receptors, the estrogen receptor (ER), the progesterone receptor (PR), and the human epidermal growth factor receptor 2 (HER2)." (PMID 33445710, 2021). "Triple-negative breast cancer (TNBC) refers to a subtype of breast cancer that is negative for estrogen receptor (ER), progesterone receptor (PR) and HER-2 expression." (PMID 34147061, 2021). "Triple-negative breast cancer (TNBC) is an aggressive sub-group of breast cancer that lacks the expression of progesterone receptor (PR), estrogen receptor (ER), and human epidermal growth factor receptor 2 (HER2)." (PMID 34451892, 2021). "Based on expression of estrogen receptor (ER), progesterone receptor (PR), and human epidermal growth factor receptor 2 (HER2), breast cancer can be classified into three subtypes, including ER-positive breast cancer, HER2-positive breast cancer, and triple negative breast cancer (TNBC)." (PMID 32350394, 2020). "As a special subtype of breast cancer, triple-negative breast cancer (TNBC) lacks the expression of estrogen receptor (ER), progesterone receptor (PR), and epidermal growth factor receptor 2 (HER2), which severely limits the clinical usage of endocrine and targeted therapy." (PMID 33299869, 2020).
breast cancer (continued). "The determination of estrogen receptor (ER), progesterone receptor (PR), human epidermal growth factor receptor (HER2), and Ki-67 were useful for defining subtypes of breast cancer which provided prognostic information and generally sufficient to guide adjuvant systemic treatment for patients." (PMID 32592349, 2020). "TNBC gets its name from its characteristic repression of gene expressions of its estrogen receptor (ER), progesterone receptor (PR), and human epidermal growth factor receptor 2 (HER2) while other breast cancers generally have at least one of these receptors over-expressed." (PMID 32080331, 2020). "A study of an Italian ORDET cohort including 391 breast cancer cases and B vitamin intake indicated that, overall, thiamine was protective and particularly protective in estrogen- and progesterone receptor-negative HER2-positive cases." (PMID 33158037, 2020). "The term triple-negative breast cancer (TNBC) is used to describe breast cancers without expression of estrogen receptor, progesterone receptor or HER2 amplification." (PMID 32085745, 2020). "Triple-negative/basal-like breast cancer is hormone-receptor negative (estrogen-receptor and progesterone-receptor negative) and HER2 negative, being more common in women with BRCA1 gene mutations." (PMID 33375317, 2020). "ER and PgR expressions of sirolimus treated and combination treated tumor are significantly lower compared to control group, hence evidently reduced tumor size of NMU-induced breast cancer." (PMID 33112549, 2020). "Considering the presence or absence of receptors results in classification of breast cancers into four therapeutic groups in clinical settings: estrogen receptor-positive (ER+), progesterone receptor-positive (PR+), HER2 amplified (HER2+) and triple negative." (PMID 33087126, 2020). "In clinical, the expression status of progesterone receptor, estrogen receptor, and human epidermal growth factor receptor 2 (HER2, overexpression and/or amplification) is of great importance for the management of breast cancer patients." (PMID 32908121, 2020). "The primary method of classifying breast cancer relies on the presence or absence of estrogen receptor (ER), the ER target gene progesterone receptor (PR), and amplification of the human epidermal growth factor receptor 2 (HER2)." (PMID 32357907, 2020). "TNBC, accounting for 15–25% of all breast cancer cases, is characterized by the lack of expression of estrogen receptor (ER), progesterone receptor (PR) and c-erbB-2 (HER2)." (PMID 32368187, 2020). "Triple-negative breast cancer (TNBC) occurs in 12–17% of breast cancer and is a subtype that does not express estrogen receptor (ER), progesterone receptor (PR) or human epidermal growth factor receptor 2 (HER2)." (PMID 31745703, 2020). "This is consistent with previous reports that identified overexpression of SMO and GLI2 in progesterone receptor (PR) negative breast cancers and gastric cancers." (PMID 32784501, 2020). "HER2-enriched breast cancer is hormone-receptor negative (estrogen-receptor and progesterone-receptor negative) and HER2 positive." (PMID 33375317, 2020). "Luminal A breast cancer is hormone-receptor-positive (estrogen-receptor and/or progesterone-receptor-positive), HER2 negative, and has low levels of the protein Ki-67, which helps control how fast cancer cells grow." (PMID 33375317, 2020). "Breast cancer, in turn, is divided into different subtypes based on the presence or absence of the estrogen receptor (ER), progesterone receptor (PR), and HER2 receptor." (PMID 32211045, 2020). "Breast cancer (BC) is a very heterogeneous disease characterized by different molecular and histopathological features; responses to treatment of its subtypes differ based on estrogen receptor, progesterone receptor, and human epidermal growth factor receptor 2 (HER2) status." (PMID 32375881, 2020).
breast cancer (continued). "Triple-negative breast cancer (TNBC) refers to breast cancer tumor cells that do not express estrogen receptor (ER), progesterone receptor (PR), and human epidermal growth factor receptor 2 (Her-2)." (PMID 32034579, 2020). "The crosstalk between progesterone receptor, stimulated by progesterone and its analogues results in RANKL to RANK binding and activation of cell proliferation and subsequently unlimited expansion of the breast cancer cells." (PMID 32183159, 2020). "Human triple-negative breast cancer (TNBC) corresponds to the basal-like subtype of breast cancer that is negative for estrogen receptor (ER), progesterone receptor (PR), and human epidermal growth factor receptor 2 (HER2)." (PMID 32169087, 2020). "Triple negative breast cancer (TNBC) which is defined by the lack of estrogen receptor (ER), progesterone receptor (PR), and human epidermal growth factor receptor-2 (Her-2) accounts for 10–20% of all breast cancer." (PMID 33552956, 2020). "About 10–15% of all breast cancers are estrogen receptor (ER), progesterone receptor (PR) and Her 2 Neu negative, referred to as triple negative breast cancers (TNBC)." (PMID 33175907, 2020). "The comparison of the protein progesterone receptor (PGR) abundance between MAP3K1 mutated and non-mutated samples in breast cancer (BRCA) is shown as an example." (PMID 33193699, 2020). "Triple negative breast cancer (TNBC) accounts for about 15% of breast cancers and is defined by the lack of expression of estrogen receptor (ER) and progesterone receptor (PR), and the absence of Her2 overexpression." (PMID 31963783, 2020). "Triple negative breast cancer (TNBC) is a subtype of breast cancer lacking expression of estrogen receptor (ER), progesterone receptor (PgR) and human epidermal growth factor receptor 2 (HER2)." (PMID 32605126, 2020). "Oncologists define luminal A as estrogen receptor (ER) > 1%, progesterone receptor (PR) ≥ 20%, breast cancer with negative human epidermal growth factor receptor-2 (HER2), and Ki-67 < 14% of clinical cases." (PMID 33267822, 2020). "Triple-negative breast cancer (TNBC) is an aggressive subtype of breast cancer that lacks expression of the estrogen receptor (ER), progesterone receptor (PR), and human epidermal growth factor receptor (HER2)." (PMID 33415093, 2020). "Triple-negative breast cancer (TNBC) is a breast cancer subtype that lacks estrogen receptor (ER) and progesterone receptor (PR) expression and does not exhibit human epidermal growth factor receptor 2 (HER2) amplification." (PMID 32555285, 2020). "Breast cancer is comprised of four subtypes that can be defined by either the positive or the negative status of the estrogen receptor (ER), progesterone receptor (PR), and human epidermal growth factor receptor 2 (HER2)." (PMID 35582044, 2020). "We had previously shown that TTP represses the transactivation activity or different steroid nuclear receptors including ERα, progesterone receptor, androgen receptor and glucocorticoid receptor without affecting their protein levels in breast cancer cells." (PMID 33117284, 2020). "TNBC is a heterogeneous subtype of breast cancer lacking estrogen receptor (ER), progesterone receptor (PR), and HER2 expression." (PMID 32276500, 2020). "Normal-like breast cancer is similar to luminal A disease: hormone-receptor-positive (estrogen-receptor and/or progesterone-receptor-positive), HER2 negative, and has low levels of the protein Ki-67, which helps control how fast cancer cells grow." (PMID 33375317, 2020). "MDA-MB-231 is a type of triple-negative breast cancer cell line with negative expression of estrogen receptor (ER), progesterone receptor (PR), and human epidermal growth factor receptor 2 (Her2), and usually as endogenous resistant breast cancer cells." (PMID 32528278, 2020).